RRN3P3 (RRN3 pseudogene 3)
Gene: Transcribed unprocessed pseudogene on chromosome 16 (22,429,796 to 22,435,812, reverse strand). Ensembl gene ENSG00000257122.
Diseases named in the same sentence as RRN3P3 in open-access papers:
RRN3P3 is named in the same sentence as 2 diseases in open-access papers, as found by Europe PMC text mining. Sharing a sentence is not in itself a finding about the gene and the disease. The quoted sentences say what the papers report.
breast carcinoma (2 papers, 2020 to 2023). "RRN3P3 has been reported as an oncogenic pseudogene in breast cancer due to its correlation with lower overall survival in high-risk patients in combination with other pseudogenes, especially in patients with the basal-like subtype." (PMID 38132443, 2023).
tumor (3 papers, 2020 to 2023). "The composite plot indicated that SDHAP1, SDHAP3, DDX12P, CLUHP3, and RRN3P3 demonstrated high expressions in the low-risk subtype, which were categorized as tumor-suppressor pseudogenes in our study." (PMID 36438489, 2022). "We found that the oncogene PDIA3P1, and tumor-suppressor RRN3P3, promote the RNA and protein expression of their targeted immune-involved genes AKT1 and EZH2 via miR-34a-5p and miR-26b-5p, respectively." (PMID 36438489, 2022). "M6A-seq identified two m6A peaks on oncogene pseudogene PDIA3P1 and one m6A peak on tumor-suppressor pseudogene RRN3P3, and the m6A-LAIC-seq data showed that full-length RNAs of pseudogenes were significantly enriched in m6A positive fraction." (PMID 36438489, 2022). "Tumor-suppressor pseudogene RRN3P3 upregulated the expression of EZH2 by competitively binding hsa-miR-26a-5p and hsa-miR-26b-5p, which explained the higher expression of EZH2 in the low-risk subtype." (PMID 36438489, 2022). "We experimentally validate the oncogene PDIA3P1, and tumor-suppressor RRN3P3, which promote the RNA and protein expression of their targeted immune-involved genes AKT1 and EZH2 via miR-34a-5p and miR-26b-5p, respectively." (PMID 36438489, 2022). "Compared to HPV negative, patients with HPV positive had significantly higher expressions of oncogene pseudogenes (SDHAP1, SDHAP3, DDX12P, CLUHP3, and RRN3P3), but there was no prominent difference in the expressions of tumor-suppressor pseudogenes (PDIA3P1, LDHAP4, LDHAP7, EEF1A1P6, and EEF1A1P11)." (PMID 36438489, 2022).